ETV5 (ETS variant transcription factor 5)
Diseases named in the same sentence as ETV5 in open-access papers (continued):
Sharing a sentence is not in itself a finding about the gene and the disease.
melanoma (11 papers, 2015 to 2026). A malignant, usually aggressive tumor composed of atypical, neoplastic melanocytes. "These inactivating mutations stabilized ETV5 in a BRAFV600E melanoma cell line and conferred resistance to MAPK pathway inhibition." (PMID 40643496, 2025). "We hypothesized that melanoma contains a poorly differentiated tumor subpopulation characterized by an ETV5-centered transcriptional program and TGF-β-associated intercellular crosstalk, which may contribute to malignant progression and immune evasion." (PMID 42079653, 2026). "Overall, these observations suggest that CDK6 up-regulated by TFs JUN and ETV5 might be associated with BRAFi resistance in melanoma patients." (PMID 32413516, 2020). "We found that patient mutations in COP1 or DET1 inactivated CRL4COP1/DET1 in melanoma cells, stabilized ETV1, ETV4, and ETV5, and conferred resistance to inhibitors of the MAPK pathway." (PMID 40643496, 2025). "ETV5 and other PEA3 family members, as well as several other ETS factors, are widely implicated in various cancer entities such as prostate, Ewing and melanoma tumours." (PMID 31937834, 2020). "We found that ETV5 deletion restored sensitivity to BRAF inhibition by PLX4720 in melanoma cells and ETV5 was the top hit of the genes that were more essential in M238R1 cells under the BRAFi treatment." (PMID 32413516, 2020). "Whether ETV5 modulates their differentiation also in pig or it affects γδ-mediated immune response in porcine melanoma remains undetermined." (PMID 29963229, 2018). "In melanoma, several ETS TFs, including FLI1, SPI1, ELF4, ETV7, SPIB, and SPIC, are expressed at higher levels in Cluster A patients, whereas ETV5, ETV4, ELK1, ERF, and ETV2 showed increased expression in Cluster B patients." (PMID 41502516, 2025). "In particular, ELK3, ETS1, ETV1, ETV4, ETV5, and SPI1 were significantly upregulated in melanoma, whereas EHF, ELF3, ELF5, ERG, ETS2, ETV7, and SPDEF were significantly downregulated in the tumor." (PMID 33424867, 2020). "We identify the JUN family transcription factors and the ETS family transcription factor ETV5 as key regulators of CDK6, which together enable resistance to BRAF inhibitors in melanoma cells." (PMID 32413516, 2020). "Through loss-of-function screens, transcriptomics, and epigenetic profile analysis, we have identified a network that includes CDK6, ETV5, and JUN as the potential mechanism for BRAFi-resistant melanoma cells." (PMID 32413516, 2020). "In human melanoma cells, CIC represses mRNA expression of the PEA3 subfamily of ETS transcription factors, namely ETV1, ETV4 and ETV5." (PMID 26683696, 2015). "In addition, no studies have reported on the expression and function of ELK3, ETV5 ELF3, ELF5, ETS2, and SPDEF in melanoma." (PMID 33424867, 2020). "Additional evidence that CDK6, ETV5, and JUN may confer resistance to BRAF inhibition comes from our analysis of two independent melanoma cohorts." (PMID 32413516, 2020). "In melanoma, the polyoma enhancer activator 3 (PEA3) subfamily, particularly ETV4 and ETV5, showed a negative correlation with immune infiltration." (PMID 41502516, 2025).
endometrial cancer (8 papers, 2014 to 2023). Primary or metastatic malignant neoplasm involving the endometrium (mucous membrane that lines the endometrial cavity). "For example, the overexpression of ETV5 in endometrial cancer cells was associated with an increased expression of N-cadherin." (PMID 29069764, 2017). "Overexpression of ETV5 is associated with elevated levels of fibronectin, α5 integrin, β1 integrin, and N-Cadherin, as well as diminished levels of Cyclin D1 and β-Catenin, promoting a more invasive phenotype of endometrial carcinoma." (PMID 36872348, 2023). "In agreement with our observation, inhibition of NID1 reduced the migration and invasion of ETV5-overexpressed endometrial cancer cells." (PMID 28416770, 2017). "In endometrial cancer, ETV5 could promote the invasion potential of tumor cells by up-regulating the expression of the zinc finger E-box binding homeobox 1 (ZEB1) gene and down-regulating the expression of epithelial (E)-cadherin." (PMID 34736492, 2021). "Also, a study investigating the targets of ETV5 in an endometrial carcinoma model has evidenced a regulation of adhesion molecules and epithelial-mesenchymal transition (EMT) genes." (PMID 29963229, 2018). "In addition, inhibition of NID1 reduced the migration and invasion of ETV5 overexpressing endometrial cancer cells." (PMID 28416770, 2017). "In addition to reinforce the role of ETV5 during the initial events of metastasis in endometrial cancer, these results link the promotion of a plasticity phenotype in CTC with their capacity to metastasize." (PMID 25261936, 2014). "In endometrial carcinoma, BDNF/TrkB-ERK was found to upregulate ETV5, which mediates the invasive phenotype of cancer cells." (PMID 36872348, 2023). "In endometrial carcinoma, BDNF-TrkB upregulates ETV5 through ERK-MAPK signaling (lower)." (PMID 36872348, 2023). "Similarly, ETV5 induces the epithelial–mesenchymal transformation of endometrial cancer through transcriptional activation of the nidogen-1 (NID1) and nuclear protein 1 (NUPR1) genes, participating in the process of endometrial cancer invasion." (PMID 34736492, 2021).
breast cancer (7 papers, 2017 to 2025). A primary or metastatic malignant neoplasm involving the breast. "In breast cancer, the selective estrogen receptor modifier, tamoxifen, inhibits the expression of ETV4 and ETV5 messenger ribonucleic acid (mRNA), which could reduce the risk of breast cancer." (PMID 34736492, 2021). "ETS variant transcription factor 5 (ETV5), also called ERM, belongs to the PEA3 subfamily (ETV1, ETV4, and ETV5), was first reported to have a potential role in the regulation of breast cancer growth and progression." (PMID 33931578, 2021). "ETV5, a member of the subfamily of PEA3 (ETV1, ETV4, and ETV5), has a prominent role in regulating the progression of human breast cancer and thyroid cancer." (PMID 33931578, 2021). "The effects of oncogenic Etv4 and Etv5 on these processes in a subset of target genes strengthen our understanding of their roles in breast cancer cells." (PMID 28446749, 2017). "Upregulation of ETV5 has been described in endometrial, ovarian and breast cancers, and chondrosarcomas, where it correlates with tumour infiltration and poor prognosis and regulates the expression of genes involved in epithelial-mesenchymal transition (EMT) and invasion." (PMID 30952872, 2019). "Expression of Etv5 also correlates with a poor prognosis of breast cancer patients." (PMID 28446749, 2017). "Furthermore, ETV5 knockdown was shown to decrease malignant potential of mammary cancer cells." (PMID 30952872, 2019). "In breast cancer, ETV4 and ETV5 are also involved in the maintenance of cancer stem cells and their self‐renewal via the regulation of sox2 or Sonic Hedgehog signalling." (PMID 40275610, 2025).
glioma (7 papers, 2018 to 2023). A benign or malignant brain and spinal cord tumor that arises from glial cells (astrocytes, oligodendrocytes, ependymal cells). "We analyzed the expression of the major ETS-factors ETS1, GABPA, and GABPB with its splice variants, ETV1, ETV4 and ETV5 all of which were widely expressed across our glioma cell panel." (PMID 31391125, 2019). "By analyzing the patient survival rates in TCGA glioma datasets, we elucidated the clinical significance of the regulation of ETV5 and FBXW9 by IGFBP5." (PMID 36949068, 2023). "Although our analysis revealed a considerable level of correlation between high ETV5 or FBXW9 expression and poor prognosis in patients with glioma, further studies are required to reveal the mechanical role of ETV5 and FBXW9 in GSC invasion and tumorigenesis." (PMID 36949068, 2023). "Graph complexity analysis in low-grade glioma has shown Etv5 and its network expression to be critical features of the neoplastic state." (PMID 33671331, 2021). "Future mechanistic studies will be required to address the relationships between NF1/RAS/MEK/ERK pathway function, ETV5 network regulation, and NF1-associated low-grade glioma formation or maintenance." (PMID 29787563, 2018). "Using both networks simultaneously, we were able to identify the Etv5 network as a defining feature of the neoplastic state in mouse and human low-grade glioma tumors." (PMID 29787563, 2018). "In both the pediatric and the juvenile pilocytic astrocytoma datasets, ETV5 was differentially expressed in the tumor groups relative to the non-neoplastic samples, similar to that observed in the mouse low-grade gliomas." (PMID 29787563, 2018). "Given the potential involvement of IGFBP5, ETV5, and FBXW9 in the invasive potential of GSCs, we subsequently aimed to identify associations between the expression of these three genes and patient survival using TCGA glioma datasets." (PMID 36949068, 2023). "Aberrant expression of ETV5 during neurodevelopment results in increased gliogenesis, and targeted expression of ETV5 blocked neural stem cell depletion and tumorigenesis in a mouse model of glioma formation." (PMID 34433050, 2021). "Next, we identify a single transcription factor, Etv5, not previously implicated in low-grade glioma, as the gene most differentially central: As such, Etv5 was the gene most central in the tumor network, and was not central in the normal network." (PMID 29787563, 2018). "Since ETV5 expression is not a hallmark of any particular neoplastic cell type in the low-grade gliomas, it is most likely that the network established reflects aberrant RAS activation in numerous cell types in the tumor." (PMID 29787563, 2018). "Relevant to our study, ETV5 levels are elevated in many tumors, including glioma." (PMID 29787563, 2018). "While this approach nicely illustrates the value of computational and bioinformatic approaches for characterizing the neoplastic state relative to its non-neoplastic counterpart, further investigation is required to understand the mechanistic role of Etv5 in glioma formation and maintenance." (PMID 29787563, 2018). "Glioma patients with high ETV5 or FBXW9 expression experienced worse survival than those with low expression, and high IGFBP5 expression in combination with high ETV5 or FBXW9 expression was significantly associated with the worst survival rate among all the groups." (PMID 36949068, 2023). "In addition, ETV5 function is required to sustain Nf1-deficient high-grade glioma growth, but had not been previously implicated in low-grade gliomas." (PMID 29787563, 2018). "PEA3 subfamily of ETS proteins (ETV1, ETV4, ETV5) amplify transcriptional signals when RAS/MAPK signaling pathway is active, and abolishing Ets activity leads to a block in glioma initiation." (PMID 31806013, 2019).
glioma (continued). "In addition, the deployment of multiple computational and statistical analysis strategies, as well as biological validation across species and time further strengthen the idea that Etv5 may be a central control element in establishing and/or maintaining low-grade gliomas." (PMID 29787563, 2018). "Finally, to determine whether differential ETV5 expression is also a feature of human pediatric low-grade gliomas (pilocytic astrocytoma; PA), we leveraged the only two human RNA microarray datasets that contained reference non-neoplastic tissue for comparison (GSE42656 and GSE12907)." (PMID 29787563, 2018). "Therefore, the increase ETV5 and FBXW9 expression in response to IGFBP5 has a negative impact on the survival of patients with glioma." (PMID 36949068, 2023).
lung carcinoma (7 papers, 2020 to 2025). "Etv5 deficiency also reduced ATII cell proliferation in the Kras model of lung cancer." (PMID 32366033, 2020). "Interestingly, knockdown of either ETV4 or ETV5 strongly inhibited the growth of human KRAS-mutant lung cancer cell lines, suggesting that the requirement for these transcription factors extends to human lung cancer." (PMID 41219537, 2025). "We also established the prognostic value of modules associated with targets of ETV5 transcription factor, translational elongation, G protein-coupled receptor (GPCR) signaling, and ribonucleoprotein (RNP) sub-unit organization in KRAS-mutant lung cancers." (PMID 36950380, 2023). "Kras activates Etv5 in lung cancer but it remains to be determined whether this is the critical stimulus in lung injury." (PMID 32366033, 2020). "We found that the regions of differential methylation significantly overlapped with binding sites of Xbp1 and Etv5, transcription factors known to play a role in lung cancer tumorigenesis, suggesting that these methylation changes could interfere with transcription factor binding." (PMID 40429836, 2025).
ovarian carcinoma (7 papers, 2015 to 2023). A malignant neoplasm originating from the surface ovarian epithelium. "In ovarian cancer, ETV5 was found to promote cell proliferation, migration and invasion through the regulation of lncRNA CTBP1-DT." (PMID 36872348, 2023). "In ovarian cancer cells, ETV5 was found to contribute to the acquisitions of resistance to PTX, and the level of ETV5 protein is mediating by the miR-1307-CIC axis." (PMID 36872348, 2023). "High levels of ETV5 mRNA are detected in human ovarian cancer, but the protein is almost undetectable in the corresponding tissues." (PMID 36872348, 2023). "Western blotting and qRT-PCR were used to detect the protein and mRNA expression of ETV5 in six ovarian cancer (OC) and human embryonic cell lines." (PMID 34736492, 2021). "In order to test if ETV5 is required for the expression of E2F targets in RAS-driven ovarian cancer cells we revisited the HEY cell line, which carries a KRASG12D mutation, as well as gain of the KRAS gene." (PMID 25557169, 2015). "We identified the ETS member ETV5 as a critical downstream effector of MAPK signaling in ovarian cancer cells." (PMID 25557169, 2015). "In addition, the Fgf-responsive gene Etv4 and its close family member Etv5 are overexpressed in certain ovarian cancers." (PMID 28873404, 2017). "ETV5 was found to promote angiogenesis via transcriptional activation of Cadherin 5, which upregulated MMP9 expression in ovarian cancer cell lines." (PMID 36872348, 2023). "We verified increased expression of Etv4 and Etv5 in MOSE-HRAS cells, suggesting that this model recapitulated the differences we observed in CCNE1 and RTK/RAS-driven ovarian cancers." (PMID 25557169, 2015). "In ovarian cancer, OV90 cells with downregulation of ETV5 exhibited an increase of ROS production." (PMID 36872348, 2023). "Using data from TCGA and GTEX, the mRNA expression levels of RECQL4, PRKCL, CCNE1, and ETV5 were found to be increased in ovarian cancer compared to normal FT tissues." (PMID 33014878, 2020).
type 2 diabetes (7 papers, 2011 to 2026). "An example of overexpression of an miRNA in type 2 diabetes is miR-200c, which decreases the expression of ETS variant transcription factor 5 (ETV5), causing disruption to insulin exocytosis." (PMID 41174263, 2026). "MiR-200c directly binds the 3′-untranslated terminal region (UTR) of ETV5 mRNA and reduces ETV5 expression, which decreased glucose-stimulated insulin secretion in type 2 diabetes." (PMID 36872348, 2023). "The risk of type 2 diabetes has only been addressed in two other studies, and here association between TMEM18, GNPDA2, ETV5, FAIM2 and SH2B1 and a BMI-dependent increased risk of type 2 diabetes have been reported." (PMID 21912638, 2011).
colon carcinoma (5 papers, 2016 to 2022). "Further, our analysis in 1,482 colon cancer patients from five different cohorts revealed that higher ETV5 expression associates with shorter relapse-free survival (RFS) of adjCTX treated colon cancer patients (Hazard ratio = 2.09–5.43, p = 0.004–0.01)." (PMID 33658938, 2020). "Survival analysis revealed that higher ETV5 expression significantly associated with shorter RFS/DFS/PFS in colon cancer in stage II and III patients." (PMID 33658938, 2020). "The result suggests a tumor-side specific role of ETV5 in colon cancer that can affect the underlying response to chemotherapy." (PMID 33658938, 2020). "Our analysis revealed higher expression of ETV4 and ETV5 genes in colon cancer tissue compared to normal tissue in TCGA samples." (PMID 33658938, 2020). "We also checked the correlation between ETV5 and colon cancer cell proliferating markers (MK167, MYC, MYBL2) in order to assess the effect of ETV5 over cell proliferation." (PMID 33658938, 2020). "Summary table of the Cox proportional hazard model assessing the effect of ETV5 expression over adjCTX-treatment response in colon cancer patients." (PMID 33658938, 2020). "PEA3 subfamily of ETS transcription factors (ETV1, ETV4, and ETV5) are upregulated in multiple cancers including colon cancers." (PMID 33658938, 2020). "After observing that ETV4 and ETV5 are overexpressed in colon cancerous tissue from TCGA cohort, we studied their role in predicting adjCTX response in colon cancer using three publicly available datasets." (PMID 33658938, 2020). "Our analysis identified and validated ETV5 expression as a predictive marker for 5-FU-based adjCTX response in stage II and II colon cancer patients." (PMID 33658938, 2020). "After observing that ETV5 expression predicts the treatment response in colon cancer, we checked the expression level of ETV5 in stage II/III CC patients (both treated and untreated) with proximal and distal tumors as the gene expression can vary with the location of the tumor." (PMID 33658938, 2020). "Additionally, we explored the role of ETV4 and ETV5 in 5-FU-based-adjCTX response prediction utilizing three publicly available colon cancer patient cohorts." (PMID 33658938, 2020). "Further, we validated the findings in colon cancer patients treated with adjuvant therapy in MCC, metastatic, and GSE14333 cohorts indicating that ETV5 is a strong predictor of disease-free survival." (PMID 33658938, 2020). "We did not observe a significant effect of ETV5 over survival response of untreated patients suggesting that ETV5 does not predict a worse prognosis in colon cancer but predicts for poor adJCTX treatment response." (PMID 33658938, 2020).
hepatocellular carcinoma (5 papers, 2021 to 2025). A malignant tumor that arises from hepatocytes. "In studies on hepatocellular carcinoma, YTHDF2 acts in an m6A-dependent Manner on its downstream direct target ETS variant transcription factor 5 (ETV5), regulating ETV5 mRNA translation to negatively modulate its protein levels and thereby influence VEGFA production." (PMID 40986143, 2025). "In hepatocellular carcinoma (HCC), YTHDF2 facilitates the m6A-dependent translation of ETS variant transcription factor 5 (ETV5), which induces PD-L1 transcription and suppresses CD8 + T-cell-mediated antitumor immunity." (PMID 39987091, 2025).
infertile (5 papers, 2017 to 2021). "We compared nine types of infertility in male humans and mice, including MArrest, oligospermia and teratospermia in humans and Ing2 Knockout (KO), Bcl6 KD, Etv5 KD, Pou3f1 KD, Ikbkap KO and Dazap1 mutant in mice." (PMID 29150651, 2017). "DMRTB1 was a down-regulated common gene among MArrest, oligospermia and Ikbkap KO, GPR137B was common among teratospermia, Bcl6b and Pou3f1 KD, and LMNB2 was common among Bcl6b, Etv5 and Pou3f1 KD infertile mice." (PMID 29150651, 2017). "The fact that ETV5-null mice are infertile demonstrates the importance of ETV5 for spermatogenesis." (PMID 29019938, 2017). "Additionally, the Arpc1b gene was up-regulated in Bcl6b, Etv5, Pouf31 and Dazap1 KD, and Alcam was up-regulated in Bcl6b, Etv5, Pouf31 and Ing2 KD infertile mice." (PMID 29150651, 2017). "Female knockout mice for ETV5 are infertile owing to a decreased ovulation and no interest in mating." (PMID 32408659, 2020).